NEK7 (NIMA related kinase 7)
Diseases named in the same sentence as NEK7 in open-access papers (continued):
Sharing a sentence is not in itself a finding about the gene and the disease.
colorectal cancer (3 papers, 2016 to 2024). A primary or metastatic malignant neoplasm that affects the colon or rectum. "One previous study shows a significantly increased expression level of NEK7 in colorectal cancer, and our study further proved the causal relationship between NEK7 and CRC." (PMID 38902711, 2024). "By reporting which drugs and small molecules have the potential to regulate NEK7 and related genes within Treg cells, we aim to contribute to advancing the treatment of colorectal cancer." (PMID 38902711, 2024). "Collectively, this evidence suggests that rs17583875 may potentially play a role in colorectal cancer by regulating the expression of NEK7 and LHX9." (PMID 38902711, 2024). "On one hand, this biologically substantiates the potential importance of NEK7 in colorectal cancer; on the other hand, it also suggests that Treg cells and NEK7 may influence each other—modulating Treg cells or NEK7 could have a significant impact on the role the other plays in tumor progression." (PMID 38902711, 2024). "Following a thorough analysis and retrieval, it has been determined that NEK7 and LHX9 within Activated & resting Treg %CD4 + cell, along with DN (CD4-CD8-) %leukocyte, hold promising potential as therapeutic targets for drug treatment of colorectal cancer." (PMID 38902711, 2024).
non-small cell lung carcinoma (3 papers, 2021 to 2025). A group of at least three distinct histological types of lung cancer, including non-small cell squamous cell carcinoma, adenocarcinoma, and large cell carcinoma. "Likewise, activation of NEK9 (and NEK7) promoted the activation of oncogenic EML4–ALKv3 and V5 fusion proteins that are involved in the progression of certain cancers, including non-small cell lung cancer (NSCLC) and gastric cancer." (PMID 41154634, 2025).
pancreatic cancer (3 papers, 2021 to 2025). "Downregulation of NEK7 has been shown to suppress pancreatic cancer liver metastasis and HCC progression." (PMID 38902711, 2024). "We then investigated NEK7 expression pattern in tissues resected from 90 patients with pancreatic cancer using microarray analysis and immunohistochemical analysis." (PMID 34295827, 2021). "Due to the expression of NEK7 significantly was correlated with both overall survival (Logrank P=6.395e-3) and disease-free survival (Logrank P=0.048) for pancreatic cancer patients." (PMID 34295827, 2021). "We examined NEK7 expression pattern using resected human tissues of normal pancreas and primary tumors from pancreatic cancer cases." (PMID 34295827, 2021). "We detected a significant involvement of NEK7 in the migratory, invasive and adherent capacities of pancreatic cancer cells." (PMID 34295827, 2021). "Taken together, these results indicate that downregulation of NEK7 reduced colonization and proliferation of pancreatic cancer cells and inhibited liver metastasis formation in vivo." (PMID 34295827, 2021). "Moreover, NEK7 promoted migration, invasion, adhesion, proliferation and liver metastatic ability of pancreatic cancer cells." (PMID 34295827, 2021). "Taken together, our data indicate that NEK7 promotes pancreatic cancer progression and it may be a potential marker for PDAC prognosis." (PMID 34295827, 2021). "Furthermore, we investigated the correlation between NEK7 expression and overall survival and disease-free survival of the 90 pancreatic cancer patients with surgical resection." (PMID 34295827, 2021). "We further investigated NEK7 expression in human pancreatic ductal epithelial cell (HPNE) cells and pancreatic cancer cell lines." (PMID 34295827, 2021). "In our study, we examined NEK7 expression pattern in PDAC and investigated its functional effect on pancreatic cancer progression." (PMID 34295827, 2021). "Additionally, using in silico analysis, Dr. Adrees and colleagues identified boeravinone B as a compound that targets NEK7 and PPP1CA proteins, which are overexpressed in pancreatic ductal adenocarcinoma, suggesting that targeting NEK7 may be a promising approach for pancreatic cancer." (PMID 40076620, 2025).
pancreatic ductal adenocarcinoma (3 papers, 2023 to 2025). An infiltrating adenocarcinoma that arises from the epithelial cells of the pancreas. "Furthermore, both NEK6 and NEK7 have negative correlations for patient survival outcomes in liver hepatocellular carcinoma and pancreatic ductal carcinoma." (PMID 37046733, 2023).
pneumonia (3 papers, 2021 to 2026). An acute, acute and chronic, or chronic inflammation focally or diffusely affecting the lung parenchyma, caused by an infection in one or both of the lungs (by bacteria, viruses, fungi, or mycoplasma.). "Taken together, these data demonstrated that the NLRP3 inflammasome was activated in S. aureus-induced pneumonia, accompanied by decreased NEK7 protein levels." (PMID 34603335, 2021). "Biomarkers including NEK7 and CAV1 were associated with the risk of pneumonia." (PMID 38137330, 2023). "Interestingly, our study found that the protein level of NEK7 was decreased in S. aureus induced mouse pneumonia." (PMID 34603335, 2021).
retinoblastoma (3 papers, 2016 to 2021). A malignant tumor that originates in the nuclear layer of the retina. "The role of NEK7 in prompting retinoblastoma progression was first discovered in a refined meta-analysis of retinoblastoma copy numbers." (PMID 33364979, 2020). "Using our integrative genome-wide approach, our study now also identified NEK7 as novel 1q candidate gene potentially driving retinoblastoma progression." (PMID 27115612, 2016). "Besides the well-established driver genes RB1 (13q-loss) and MYCN (2p-gain) we identified CRB1 and NEK7 (1q-gain), SOX4 (6p-gain) and NUP205 (7q-gain) as novel retinoblastoma driver candidates." (PMID 27115612, 2016). "Nevertheless, a later study demonstrated that silencing NEK7 resulted in reduced CDK2, cyclin D1, and cyclin E levels in vitro, which therefore significantly inhibited retinoblastoma cell (Y79, SO-RB50 and WERI-RB1) proliferation." (PMID 33364979, 2020).
type 2 diabetes (3 papers, 2020 to 2025). "NEK7, encoding NIMA-related kinase 7, is a crucial factor involved in chronic immune inflammation in type 2 diabetes by triggering the activation of the NLRP3 inflammasome complex." (PMID 41465472, 2025). "Mechanistically, NEK7 (NIMA‐related kinase 7), which can be suppressed by miR‐23a‐3p, is highly expressed in type 2 diabetes mellitus patients and rats." (PMID 34590363, 2021).
diabetic retinopathy (2 papers, 2025 to 2026). "In order to verify whether MCC950 can block the NEK7/NLRP3 pathway in diabetic retinopathy by binding specifically with NLRP3 and thus achieve the therapeutic effect, we used immunofluorescence localization to analyze the NEK7 expression level in the retina." (PMID 40987781, 2025).
injury (2 papers, 2021 to 2023). Damage inflicted on the body as the direct or indirect result of an external force, with or without disruption of structural continuity. "Further evidence was provided by in vivo study, which showed that disruption of Gli1 reversed myeloid Foxo1 deficiency-mediated cytoprotection, evidenced by augmented IR-induced liver injury and enhanced NEK7/NLRP3 activity." (PMID 33288903, 2021).
multiple sclerosis (2 papers, 2018 to 2019). A progressive autoimmune disorder affecting the central nervous system resulting in demyelination. "Regarding its in vivo functions, NEK7-deficient mice with multiple sclerosis showed less IL-1β-related inflammatory disorders than wild-type mice." (PMID 31787755, 2019). "Moreover, compared to wild-type mice, NEK7-deficient mice with multiple sclerosis present with fewer IL-1b-related inflammatory diseases." (PMID 30202244, 2018).
osteoarthritis (2 papers, 2025). A noninflammatory degenerative joint disease occurring chiefly in older persons, characterized by degeneration of the articular cartilage, hypertrophy of bone at the margins and changes in the synovial membrane. "A recent study has shown that OGT-induced NEK7 O-GlcNAcylation levels were increased in both osteoarthritis and its experimental models, and knockout of OGT could alleviate osteoarthritis progression in model mice." (PMID 41350524, 2025).
staphylococcus aureus infection (2 papers, 2021 to 2022). An infectious process in which the bacteria Staphylococcus aureus is present. "In addition, the latest research shows that Staphylococcus aureus infection activates NLRP3 inflammasome through Nek7 and K+ efflux signaling." (PMID 35350616, 2022).
benign prostate hyperplasia (1 paper, 2024). "In this study, P2X7R, NEK7, and GSDMD-NT expression levels were detected in prostate tissues from benign prostate hyperplasia (BPH) patients and experiment autoimmune prostatitis (EAP) mice." (PMID 38993566, 2024).
brain injury (1 paper, 2022). Acute and chronic (see also brain INJURIES, CHRONIC) injuries to the brain, including the cerebral hemispheres, CEREBELLUM, and brain STEM. "Chen and his colleagues believed that NEK7 could alleviate neuroinflammation and nerve injury produced by traumatic brain injury (TBI) by affecting pyroptosis." (PMID 36177039, 2022).
cervical cancer (1 paper, 2018). A primary or metastatic malignant neoplasm involving the cervix. "Presently, research on NEK7 has been mainly concentrated in the field of malignant tumorigenesis, and this protein is closely related to the occurrence of breast and cervical cancer." (PMID 30202244, 2018).
cyst (1 paper, 2021). A sac-like closed membranous structure that may be empty or contain fluid or amorphous material. "Interestingly, LKB1 (STK11) was shown to be part of a ciliary module comprising NPHP1, NEK7, ANKS3 and polycystin-1 that regulates cilia-controlled secretion of CCL2, a chemokine that promotes macrophage recruitment and consequent cyst growth and interstitial inflammation." (PMID 34055783, 2021).
depression (1 paper, 2025). "NEK7 is under scrutiny for its regulatory role in NLRP3 activation in various diseases, including depression." (PMID 39005130, 2025). "Additionally, we discovered that VTX, an antidepressant known for its cognitive benefits in depression, notably counteracts the abnormal NLRP3 inflammasome expression, particularly in the dorsal hippocampus 24 h after LPS exposure, potentially via regulating NEK7 expression." (PMID 39005130, 2025).
esophageal adenocarcinoma (1 paper, 2023). A malignant tumor with glandular differentiation arising predominantly from Barrett mucosa in the lower third of the esophagus. "Considering that Barrett’s related esophageal adenocarcinoma is an inflammation-related disease, the role of NEK7 in Barrett’s tumorigenesis deserves further investigation." (PMID 37835513, 2023).
gastric cancer (1 paper, 2021). A primary or metastatic malignant neoplasm involving the stomach. "By using RNA-seq data of gastric cancer from TCGA, we analyzed genetic correlation and obtained a gene map positively and negatively associated with NEK7." (PMID 34419048, 2021). "Bioinformatics analysis revealed that NEK7 is upregulated in gastric cancer and is related to poor prognosis." (PMID 34419048, 2021). "Ultimately, we revealed how NEK7 promotes gastric cancer proliferation and analyze the mechanism of promoting the progression of gastric cancer." (PMID 34419048, 2021). "Then, CCK-8 assay, flow cytometry, and EDU assay were utilized to investigate the effect of NEK7 on gastric cancer cell proliferation." (PMID 34419048, 2021). "NEK7-downregulated in vitro gastric cancer models were established based on MGC-803 and MKN-45 cells." (PMID 34419048, 2021). "Further analysis showed that NEK7 was correlated with infiltration of multiple immune cells as well as gastric cancer-related pathways." (PMID 34419048, 2021). "We analyzed the expressions of NIMA kinases and their effects on prognosis synthetically and found that only NEK7 is upregulated in gastric cancer and exerted a significant effect on gastric cancer prognosis." (PMID 34419048, 2021). "A mouse subcutaneous model revealed the regulating effect of NEK7 on gastric cancer cell proliferation in vivo." (PMID 34419048, 2021). "The results showed that only the expression level of NEK7 was upregulated in gastric cancer (|LogFC|> 1, p < 0.01 was significant) and predicted poor survival prognosis." (PMID 34419048, 2021). "The results showed that downregulation of NEK7 could inhibit proliferation of gastric cancer cells, reduce the proportion of neoplastic gastric cancer cells, and lead to cell cycle G1/S arrest." (PMID 34419048, 2021). "Immune infiltration analysis shows that NEK7 is closely related to the infiltration of macrophages, especially M2 macrophage that could promote gastric cancer metastasis, cell proliferation, and tumor progression." (PMID 34419048, 2021). "In brief, these results demonstrate that NEK7 could promote gastric cancer cell proliferation in vivo." (PMID 34419048, 2021). "We obtained RNA-seq (RNA-sequencing) data and the corresponding clinical information of 375 gastric cancer samples in The Cancer Genome Atlas Stomach Adenocarcinoma (TCGA-STAD) dataset to analyze the relationship between NEK7 expression level and clinical–pathological grading and staging." (PMID 34419048, 2021). "We hold the view that NEK7 could promote gastric cancer progression through not only regulation of cancer cell proliferation directly but also cell interaction, which could regulate immune infiltration and changes in immune cell subsets." (PMID 34419048, 2021). "Ultimately, NEK7 could promote gastric cancer cell proliferation both in vitro and vivo." (PMID 34419048, 2021). "In this study, the results of the bioinformatic analysis showed that among NEKs, the expressions of NEK2, NEK6, and NEK7 are upregulated, whereas NEK3 and NEK7 are related to the poor prognosis of gastric cancer." (PMID 34419048, 2021). "Although those studies have revealed the connection between NEK7 and malignancies, NEK7 has not yet been reported in gastric cancer." (PMID 34419048, 2021). "The expression of NEK7 is positively related to the infiltration of Treg cells, macrophages, monocytes, neutrophils, and M2 macrophages in gastric cancer, even if it has no distinct correlation with infiltration of M1 macrophages." (PMID 34419048, 2021). "Cell experiments indicated the promoting effect of NEK7 on cell proliferation, while the absence of NEK7 could lead to inhibition of gastric cancer proliferation and G1/S arrest." (PMID 34419048, 2021).
glioblastoma (1 paper, 2023). The most malignant astrocytic tumor (WHO grade IV). "Similar observations were observed for glioblastoma cells, with depletion of either NEK6 or NEK7 leading to increased tubulation." (PMID 37099601, 2023). "As a further test, we performed NEK6/7 siRNA knockdown in glioblastoma cells and observed an increase in the size of EEA1-marked vesicles after depletion of NEK7 but not NEK6, suggesting cell type–specific requirements for NEK functions." (PMID 37099601, 2023).
influenza (1 paper, 2016). An acute viral infection of the respiratory tract, occurring in isolated cases, in epidemics, or in pandemics; it is caused by serologically different strains of viruses (influenzaviruses) designated A, B, and C, has a 3-day incubation period, and usually lasts for 3 to 10 days. "Knocking down NEK7 had no impact on virus replication, which suggests a non-relevant role of this particular kinase during influenza infection However, knocking down LIF increased virus replication in various influenza A strains." (PMID 27166678, 2016).
invasive ductal carcinoma (1 paper, 2021). "NEK7 expression was undetectable in normal pancreatic ducts; NEK7 was overexpressed in primary tumor of PDAC; NEK7 expression was highly correlated with advanced T stage, poorly differentiated histological grade invasive ductal carcinoma, and lymphatic invasion." (PMID 34295827, 2021).
kala-azar (1 paper, 2020). "We thought of assessing the expression of both NEK7 and TAK1 in blimp-1 deficient cells infected with promastigotes since BLIMP-1 has been found to be a key player in the pathogenesis of kala-azar." (PMID 33194842, 2020).
kidney damage (1 paper, 2018). "In addition, the mRNA and protein expression levels of NEK7, NLRP3, and ASC in LN patients were significantly lower than those in SLE patients without kidney damage, suggests that this is closely related to the occurrence of LN and could be a protective factor involved in the pathogenesis of LN." (PMID 30202244, 2018).
Listeria monocytogenes infection (1 paper, 2021). "In contrast, our recent study in Listeria monocytogenes infection found that the protein expression of NEK7 was increased." (PMID 34603335, 2021).
liver fibrosis (1 paper, 2025). "More importantly, NEK7 overexpression effectively alleviates CCl4- and choline-deficient, high-fat diet-induced liver fibrosis." (PMID 41315267, 2025). "This indicated that aggravation of CCl4-induced liver fibrosis in the Het mice may be due to the further deterioration of complex II activity caused by NEK7 deficiency." (PMID 41315267, 2025). "In this study, we found that the loss of NEK7 in hepatocytes leads to RET, which not only triggers spontaneous liver fibrosis but also aggravates the progression of CCl4-induced hepatic fibrosis." (PMID 41315267, 2025). "In vivo, we used hepatocyte NEK7 knockdown mice (the Het mice) and the corresponding WT mice as controls to induce liver fibrosis by intraperitoneal injection of CCl4 for 6–7 consecutive weeks." (PMID 41315267, 2025). "In this study, we bred NEK7 hepatocyte specific knockout mice and found that all surviving Hom mice developed liver fibrosis at five months." (PMID 41315267, 2025). "Given the critical role of NEK7 in maintaining normal mitochondrial homeostasis in hepatocytes, the reduction of NEK7 could contribute to the pathogenesis and advancement of liver fibrosis." (PMID 41315267, 2025). "To investigate the effect of NEK7 overexpression on chronic liver disease, we constructed a liver fibrosis model in the WT mice by intraperitoneal injection of CCl4 for 6–7 consecutive weeks, during which NEK7 plasmids (pcDNA3.1-mNEK7) were injected into the tail vein every six days." (PMID 41315267, 2025). "Furthermore, in the CCl4-induced liver fibrosis model, overexpression of NEK7 specific in hepatocytes delivered by AAV8-TBG vector still did not affect the levels of NLRP3 inflammasome activation in the livers, consistent with the findings in the CDAHFD model." (PMID 41315267, 2025). "Taken together, we found that NEK7 deficiency in hepatocytes caused HSC activation and exacerbated liver fibrosis induced by CCl4, which could be reversed by inhibiting RET or ROS scavenging." (PMID 41315267, 2025). "Deficiency of NEK7 in hepatocytes induces reverse electron transport (RET) and inhibits mitochondrial respiration, thereby promoting ROS generation, triggering spontaneous liver fibrosis and aggravating CCl4-induced liver fibrosis, which can be attenuated by RET inhibitors." (PMID 41315267, 2025). "To confirm that the protective role of NEK7 is hepatocyte-specific, we further used AAV8-TBG vector to deliver NEK7 into the hepatocytes followed by CCl4 intraperitoneal injection to induce liver fibrosis." (PMID 41315267, 2025). "Here they show that mitochondria-localized NEK7 couples mitochondrial complex II subunit SDHB to maintain the homeostasis of electron transport in hepatocytes, thereby impeding the progression of liver fibrosis." (PMID 41315267, 2025). "Taken together, NEK7 overexpression alleviated liver fibrosis induced by CCl4 and CDAHFD, suggesting that NEK7 may be a promising therapeutic target for the treatment of chronic liver fibrosis." (PMID 41315267, 2025).
lupus nephritis (1 paper, 2018). Glomerulonephritis in the context of systemic lupus erythematosus. "Compared to those in SLE patients without renal damage, patients with lupus nephritis (LN) exhibited lower mRNA levels of NEK7, NLRP3, and ASC but higher levels of Caspase-1, IL-1b, and IL-18." (PMID 30202244, 2018).